PARP1 (poly(ADP-ribose) polymerase 1)
Diseases named in the same sentence as PARP1 in open-access papers (continued):
Sharing a sentence is not in itself a finding about the gene and the disease.
ankylosing spondylitis (1 paper, 2023). An autoimmune chronic inflammatory disorder characterized by inflammation in the vertebral joints of the spine and sacroiliac joints. "In macrophages, PARP1 regulates transcription, signaling, inflammatory vesicle activity, metabolism, and redox homeostasis, supporting macrophage polarization towards a pro-inflammatory phenotype (M1) and driving host defense against pathogens involved in the pathogenesis of ankylosing spondylitis." (PMID 37193965, 2023).
anxiety disorder (1 paper, 2021). A category of psychiatric disorders which are characterized by anxious feelings or fear often accompanied by physical symptoms associated with anxiety. "Since PARP-1 inhibitors appear to enhance the extinction of fear, targeting impaired extinction in anxiety disorders, such as PTSD, may prove an important and novel approach to enhance treatment efficacy." (PMID 34201014, 2021).
appendix cancer (1 paper, 2020). "Similar changes in MAPK/PI3K signaling proteins (phosphorylated‐ERK and ‐AKT) and apoptotic proteins (PUMA, cleaved caspases 3/9, PARP‐1) following drug therapy were confirmed in explant tissue from mucinous colon/appendix cancers." (PMID 31958897, 2020).
asphyxia (1 paper, 2014). A state of general hypoxia and hypercapnia (abnormally elevated carbon dioxide (CO2) levels in the blood), resulting in acidosis, which affects all tissues in the body. "PARP-1 has been involved in the long-term effects produced by perinatal asphyxia, interacting with XRCC1, DNA ligase IIIα, and DNA polymerase-β, working in tandem to repair single-strand breaks." (PMID 24723845, 2014).
ataxia telangiectasia (1 paper, 2018). Ataxia-telangiectasia is the association of severe combined immunodeficiency (affecting mainly the humoral immune response) with progressive cerebellar ataxia. "Poly(ADP-ribose) polymerase 1–dependent recruitment of UBA1 to DNA ensures ataxia-telangiectasia and RAD3-related activation." (PMID 30456359, 2018).
atopic dermatitis (1 paper, 2020). "PARP1 positively regulates the production of Th1/Th2 cytokines such as IL-4/IL-5/GM-CSF and allergen-specific IgE in a mouse model of atopic dermatitis." (PMID 32900001, 2020). "Since PARP1 facilitates the expression of IL4 upon T-responses in a model of atopic dermatitis, PARP inhibitors may indirectly interfere with IL4-induced M2 polarization." (PMID 32900001, 2020).
Atrophy (1 paper, 2022). Any weakening or degeneration, especially through lack of use. "Previous results also demonstrated that inhibition of PARP-1 may result in a better skeletal muscle performance in models of disuse-induced atrophy." (PMID 35740560, 2022).
autism (1 paper, 2021). Persistent deficits in social interaction and communication and interaction as well as a markedly restricted repertoire of activity and interest as well as repetitive patterns of behavior. "Our study has provided several pieces of evidence that address the pivotal role of PARP-1 inhibition in the mouse autism model." (PMID 33671196, 2021).
avian influenza (1 paper, 2019). Infection of domestic and wild fowl and other birds with influenza A virus. "The host factor PARP1, a poly-ADP ribosyl polymerase, was required for optimal functions of human, swine, and avian influenza RdRP in human 293T cells." (PMID 31015836, 2019).
bone osteosarcoma (1 paper, 2020). A usually aggressive malignant bone-forming mesenchymal neoplasm arising from the bone. "Interestingly, in a proteome wide study of PARylated proteins present in human bone osteosarcoma-derived UOS2 cells that do not express SHC3, the closely related protein SHC1 was identified as PARP1 target." (PMID 32443613, 2020).
cerebral aneurysms (1 paper, 2023). "In a rat model of cerebral aneurysms, treatment with 3-aminobenzamide, an anti-inflammatory compound classically used for PARP1/ARTD1 inhibition, decreased macrophage accumulation and PARP1/ARTD1 expression." (PMID 37513811, 2023).
cervix adenocarcinoma (1 paper, 2022). "A PARP1 inhibitor was shown to inhibit β-catenin signaling in HeLa (cervix adenocarcinoma) and SiHa (cervix squamous cell carcinoma) cells." (PMID 36364346, 2022).
Chagas cardiomyopathy (1 paper, 2020). A disease of the cardiac muscle developed subsequent to the initial protozoan infection by trypanosoma cruzi. "However, we surmise that PARP1 is a potential target for controlling chronic inflammatory pathology and Chagas cardiomyopathy." (PMID 32315358, 2020).
childhood-onset epileptic encephalopathy (1 paper, 2020). "CHD2 (childhood-onset epileptic encephalopathy) is recruited by PARP1 to sites of DNA damage in HEK293 and U2OS cells." (PMID 32737294, 2020).
chronic asthma (1 paper, 2017). An asthma that is characterized by the development of persistent airway inflammation and recurrent attacks of breathlessness and wheezing, which vary in severity and frequency. "It is possible that PARP-1 regulates airway remodeling in chronic asthma partly by modulating EMT process." (PMID 28974953, 2017).
clear cell renal cell carcinoma (1 paper, 2021). "We have shown that the development of clear cell renal cell carcinoma (ccRCC) is associated with extreme accumulation of pADPr caused by the enhanced expression of PARP-1 and decreased PARG levels." (PMID 34638458, 2021). "We have shown that Clear Cell Renal Cell Carcinoma (ccRCC) is prone to accumulate poly(ADPribose) due to increase in PARP-1 and decrease in PARG enzymes." (PMID 34638458, 2021).
congenital intestinal atresia (1 paper, 2024). "We also established the correlations of PARP1 and PAR expression of 10 NEC patients and 10 patients with congenital intestinal atresia with the clinical indices." (PMID 39085218, 2024).
cyst (1 paper, 2023). A sac-like closed membranous structure that may be empty or contain fluid or amorphous material. "However, at 24 days of EB formation, a significant increase in cyst-like structures was observed in PARP1ΔC/ΔC EBs compared to PARP1+/+, suggesting a differentiation defect of epithelial-like cells, which may compromise the morphogenesis of organs." (PMID 37626888, 2023). "The low amount of PARP1-ΔC and the lack of the C-terminus, which perhaps loses its engagement with critical interactors, may alter expression of genes—for example, in the extracellular matrix (e.g., ECM)—which could be responsible for the cyst phenotype of PARP1-ΔC EBs." (PMID 37626888, 2023).
cystic fibrosis (1 paper, 2012). Autosomal recessive disorder caused by pathogenic variants in the CFTR gene (cystic fibrosis transmembrane conductance regulator), which encodes a chloride and bicarbonate channel expressed in epithelial cells, and follow the diagnosis criteria. "The involvement of PARP-1 in oxidative stress, inflammatory responses, and energy maintenance, and its emerging role as a regulator of intracellular protein trafficking suggested that it may be an interesting potential target for small molecule correctors in Cystic fibrosis." (PMID 22988441, 2012).
dependent (1 paper, 2016). "Here we report that Parp1-deficient mice expressing increased Aag (AagTg/Parp1−/−) develop sex-dependent kidney failure upon exposure to the alkylating agent, methyl methanesulfonate (MMS), and suffer increased whole-animal lethality compared to AagTg and wild-type mice." (PMID 27391435, 2016).
dysplasia (1 paper, 2024). A usually neoplastic transformation of the cell, associated with altered architectural tissue patterns. "PARP1 expression was significantly increased in focal areas of BE with dysplasia and EAC, indicating feasibility of localizing such pathologic areas within BE and normal esophageal tissue." (PMID 38383387, 2024). "To determine the relevance of PARP1 for the identification of dysplasia and EAC in BE patients, we demonstrate here that PARP1 expression was low in normal squamous epithelium, slightly elevated in BE without IEN but strongly increased when IEN was present." (PMID 38383387, 2024).
encephalomyelitis (1 paper, 2017). Inflammation of the brain and the spinal cord. "Furthermore, the effects of PARP-1 on the functioning of DCs were analyzed in mouse model of encephalomyelitis and data confirmed that PARP-1 inhibition reduces the DC number as well as their APC function." (PMID 28974953, 2017).
endophthalmitis (1 paper, 2016). An infectious process affecting the internal structures of the eye. "Together, these findings imply the involvement of caspase-9 and -3 activation and PARP-1 cleavage in executing the retinal cell death in endophthalmitis." (PMID 27551524, 2016). "As the caspase and PARP-1 activation were identified as key regulators of apoptosis in S. aureus endophthalmitis, therefore, we tested whether pharmacological inhibition of caspase and PARP-1 activation can prevent retinal apoptosis." (PMID 27551524, 2016).
energy metabolism disorders (1 paper, 2020). "We also found that PARP1 inhibitors could protect SCNs from ozone exposure through avoiding energy metabolism disorders caused by NAD+ depletion." (PMID 33425964, 2020).
enterocolitis (1 paper, 2017). An inflammatory process affecting the small intestine and colon. "Down-regulation of pro-inflammatory gene expression observed in a PARP-1-depleted mouse enterocolitis model upon exposure to Salmonella typhimurium suggests that these effects might be related to the NF-κB mediated gene regulatory functions of PARP-1." (PMID 28430591, 2017).
gallbladder tumor (1 paper, 2014). "To determine whether the impact of oridonin on tumor growth inhibition was related to caspase-3, caspase-9, NF-κB, Bax, Bcl-2, PARP-1 and cytochrome c, we evaluated the levels of these apoptosis-related proteins in the gallbladder tumor tissues by western blot analysis." (PMID 24655726, 2014).
gastric ulcer (1 paper, 2024). An ulcerated lesion in the mucosal surface of the stomach. "Furthermore, both quercetin and nanoquercetin inhibited poly ADP-ribose polymerase 1 (PARP-1) and apoptosis during ethanol-induced gastric ulcer prevention." (PMID 39844873, 2024).
geographic atrophy (1 paper, 2017). "To validate the in vivo role of PARP-1 in the physiological function of the retina, we performed a fundoscopic examination to assess the geographic atrophy in live animals." (PMID 28055012, 2017).
glaucoma (1 paper, 2023). Increased pressure in the eyeball due to obstruction of the outflow of aqueous humor. "As further support for the impact of oxidative stress on DNA in glaucoma, a negative correlation between base excision repair gene expression (PARP1 and OGG1) and the 8-OHdG level has been detected in the plasma of glaucoma patients." (PMID 36837806, 2023).
Glomerular sclerosis (1 paper, 2022). Accumulation of scar tissue within the glomerulus. "The inactivation of Twist2 by an endogenous ligand or exogenous substance like NMN might regulate the expression of Nmnat1 and reduce glomerular sclerosis due to PARP1 suppression." (PMID 35962139, 2022).
H1N1 Influenza A (1 paper, 2025). "The degree, closeness, and betweenness values of 3.82, 7.54, and 23.17, respectively, indicated that three major proteins—CDC25B, PARP1, and PTGS2—are involved in the interaction between microbial isolates and H1N1 Influenza A." (PMID 40278270, 2025). "Network pharmacology indicates that CDC25B, PARP1, and PTGS2 are key target proteins involved in the interaction between S. ardesiacus isolates and H1N1 Influenza A." (PMID 40278270, 2025).
Helicobacter infection (1 paper, 2025). "In addition, the superoxide produced by Helicobacter infection in the gastric mucosa causes poly ADP‒ribose polymerase-1 (PARP-1) activation and promotes the release and development of mitochondrial apoptosis-inducing factor (AIF)." (PMID 40264171, 2025).
Hereditary breast cancer (1 paper, 2017). Breast carcinoma that has developed in relatives of patients with history of breast carcinoma. "Using a non-invasive intraductal (ID) preclinical intervention strategy, we explored the use of combined cisplatin and poly (ADP)-ribose polymerase 1 (PARP1) inhibition to prevent the development of hereditary breast cancer." (PMID 28977823, 2017).
hereditary ovarian carcinomas (1 paper, 2013). "Because PARP1 is involved in DNA repair at multiple levels, it appears to be a good target for the potentiation of the effect of complete loss of BRCA1 or BRCA2 function due to the loss of heterozygosity in hereditary ovarian carcinomas." (PMID 23344037, 2013).
Hyperammonemia (1 paper, 2022). An increased concentration of ammonia in the blood. "We tested this hypothesis by measuring the expression and activation of the apoptosis-related proteins, cleaved-caspase-3 and cleaved-poly[ADP-ribose] polymerase 1 (PARP-1), under NH4Cl-induced hyperammonemia." (PMID 35464767, 2022).
hypopharyngeal carcinoma (1 paper, 2020). Carcinoma, predominantly squamous cell, arising from the epithelial cells of the hypopharynx. "In this study, we aimed to detect the role of PARP1 in radioresistance and evaluate effect of its inhibitor, Olaparib, on radiosensitization of hypopharyngeal cancer." (PMID 31957270, 2020). "Taken together, our study demonstrated high expression of PARP1 in radioresistant FaDu‐RR cells could serve as a potential radiosensitivity biomarker for hypopharyngeal carcinoma." (PMID 31957270, 2020). "Our findings from the current study support that Olaparib can significantly inhibit PARP1 expression and consequently sensitize FaDu‐RR cell to radiotherapy, which may help individualize treatment for improved outcomes of patients with hypopharyngeal carcinoma treated with radiotherapy." (PMID 31957270, 2020). "We have been suggested that high expression of PARP1 enhances the radioresistance and Olaparib has a positive effect on the radiosensitization in hypopharyngeal cancer, providing an effective therapeutic strategy and improving their prognosis of hypopharyngeal cancer patients treated with radiation." (PMID 31957270, 2020).
infectious colitis (1 paper, 2023). A viral or bacterial infectious process affecting the large intestine. "In summary, our data demonstrate that NR treatment in mice with infectious colitis restores mitochondrial function, and surprisingly, reduces the activity of PARP1." (PMID 37744380, 2023).
ischemic disease (1 paper, 2021). Lack of blood supply to an area of the body, resulting in impairment of tissue oxygenation. "Hyperactivation of PARP1 is known to be a major cause of necrotic cell death by depleting NAD+/ATP pools during Ca2+ overload which is associated with many ischemic diseases." (PMID 33811702, 2021).
keloid (1 paper, 2019). An irregularly shaped, elevated mark on the skin caused by deposits of excessive amounts of collagen during wound healing. "Conclusively, these findings suggested that PARP1 inhibition can be a potential therapeutic target for keloid treatment and insinuated rucaparib can be a successful option for the treatment of keloid disease." (PMID 31119062, 2019). "We also revealed that PARP1 inhibition significantly inhibits the expression of keloid fibroblast in terms of cell viability, cell migration, and fibrosis marker expression." (PMID 31119062, 2019). "So, we initiated this study by analyzing baseline PARP1 expression in normal human dermal tissue and keloid tissue." (PMID 31119062, 2019). "Herein, we evaluated the therapeutic effect of PARP1 inhibitor, rucaparib, for keloids." (PMID 31119062, 2019). "The expressions of PARP1 and Smad3 were significantly higher in keloid tissue." (PMID 31119062, 2019).
left ventricular hypertrophy (1 paper, 2021). Enlargement of the LEFT VENTRICLE of the heart. "Moreover, another PARP-1 inhibitor, L-2286, can not only prevent the development of left ventricular hypertrophy in SHRs, but also modulate mitochondrial dynamics and biogenesis, indicating that PARP-1 may be a therapeutic target in hypertensive cardiac hypertrophy." (PMID 34776960, 2021).
leiomyoma (1 paper, 2013). A well-circumscribed benign smooth muscle neoplasm characterized by the presence of spindle cells with cigar-shaped nuclei, interlacing fascicles, and a whorled pattern. "Connecting with the PARP1 hub in leiomyoma from older black women were other genes involved in transcription or DNA repair including PRKDC, catenin (cadherin-associated protein), beta 1subunits, MED4, MED19 and MEDIATOR complex." (PMID 23785396, 2013).
Leukodystrophies (1 paper, 2022). "Overall, the current data indicate that PARP-1 might play a role in the mechanisms underlying leukodystrophies such as KD, X-ALD, or MLD based on the effects of PARP-1 inhibition on inflammatory and neuromodulatory mediators." (PMID 35158955, 2022). "In particular, we address the possible use of PARP-1 inhibitors in examples of rare leukodystrophies, for which there are a paucity of treatment options and an urgent need for novel therapeutic approaches." (PMID 35158955, 2022). "Finally, PARP-1 plays a pivotal role in disrupted BBB, which is observed in leukodystrophies." (PMID 35158955, 2022). "To date, there is no direct evidence of PARP-1 involvement in leukodystrophies such as KD, X-ALD, or MLD, and as of yet, there are no PARP-1 inhibitors under clinical investigation in this disease space." (PMID 35158955, 2022).
leukoplakia (1 paper, 2014). A white patch or plaque on a mucous membrane that cannot be characterized clinically or pathologically as any other disease. "Amplification of BTBD7, KHDRBS1, PARP1 and RAB1A was exclusively detected in progressive leukoplakia and corresponding OSCC." (PMID 24403051, 2014). "Amplified genes mapping within recurrent CNAs (KHDRBS1, PARP1, RAB1A, HBEGF, PAIP2, BTBD7) were selected for validation, by quantitative real-time PCR, in an independent set of 32 progressive leukoplakia, 32 OSSCs and 21 non-progressive leukoplakia samples." (PMID 24403051, 2014). "BTBD7, KHDRBS1, PARP1 and RAB1A were all found to be amplified in progressive leukoplakia lesions and OSSCs and not amplified in non-progressive leukoplakia." (PMID 24403051, 2014).
liposarcoma (1 paper, 2019). A usually painless malignant tumor that arises from adipose tissue. "In liposarcomas, the PARP1‐based classification was associated with the pathological subtypes (well differentiated/dedifferentiated, myxoid, pleomorphic), but its prognostic value persisted in multivariate analysis including these later (data not shown)." (PMID 31131495, 2019).
liver diseases (1 paper, 2020). "Other studies regarding upstream regulators of SIRT1, such as IRF9/PPAR-α, NAMPT/NMNAT, HuR, AMPK, PARP1, CK2 and cathepsins have pointed to these proteins as possible therapeutic targets for the treatment of various inflammatory pathologies, including liver diseases." (PMID 32485811, 2020).
liver toxicity (1 paper, 2018). "In summary, the present study demonstrates that PARP1, via activating PXR and promoting pro-toxic P450 enzymes, may represent a potential therapeutic target for the prevention and treatment of APAP-induced liver toxicity." (PMID 30050067, 2018).
low grade glioma (1 paper, 2024). A grade I or grade II glioma arising from the central nervous system. "Parthanatos, a cell death mechanism triggered by PARP-1 activation, is implicated in oncogenic processes, yet their role in low-grade gliomas (LGG) remains poorly understood." (PMID 38730061, 2024).
lung tumors (1 paper, 2020). "On this basis, we hypothesized that PARP-1 and PARP-2 expression and activity may be increased in lung tumors of patients with COPD." (PMID 33187221, 2020). "A decline in PARP-1 and PARP-2 protein expression was seen in lung tumors irrespective of COPD." (PMID 33187221, 2020).